ACRV1 (acrosomal vesicle protein 1)
Synonyms: SPACA2; SP-10; D11S4365
Tractability: Antibody: UniProt predicts a signal peptide or a membrane-spanning region.
Gene: Protein-coding gene on chromosome 11 (125,671,522 to 125,680,874, reverse strand). Ensembl gene ENSG00000134940.
Subcellular location: Cytoplasmic vesicle, secretory vesicle, acrosome
Subcellular location (Human Protein Atlas): Acrosome; Predicted to be secreted
Gene Ontology:
Molecular function: protein binding
Biological process: spermatogenesis
Cellular component: acrosomal vesicle; cytoplasm; vesicle
Genetic constraint (gnomAD): Loss-of-function variants: 17 observed, 31.03 expected, observed/expected ratio (o/e) 0.55, 90% interval 0.37 to 0.82. The upper end of that interval is the gene's LOEUF score, 0.82, which puts it in group 3 of 6, group 1 being the genes least tolerant of losing a copy. Missense variants: 294 observed, 334.94 expected, observed/expected ratio (o/e) 0.88, 90% interval 0.8 to 0.97. Synonymous variants: 98 observed, 118.39 expected, observed/expected ratio (o/e) 0.83, 90% interval 0.7 to 0.98.
Homologues: Orthologues: chimpanzee ACRV1 (97% identical), macaque ACRV1 (91% identical), pig ACRV1 (69% identical), rabbit ACRV1 (69% identical), dog ACRV1 (64% identical), rat Acrv1 (60% identical), guinea pig ACRV1 (60% identical), mouse Acrv1 (59% identical). Paralogues in human: PATE1 (12% identical), PATE3 (11% identical), PATE4 (11% identical), PATE2 (9% identical).
Diseases named in the same sentence as ACRV1 in open-access papers:
ACRV1 is named in the same sentence as 12 diseases in open-access papers, as found by Europe PMC text mining. Sharing a sentence is not in itself a finding about the gene and the disease. The quoted sentences say what the papers report.
pancreatic cancer (7 papers, 2015 to 2025). "The analysis of biomarkers in saliva offers an easy and noninvasive way to search for mutations in RNAs and miRNAs of genes such as MBD3L2, KRAS, ACRV1 and DPMI, among others, which could assist in differentiating pancreatic cancer patients from CP patients and healthy control." (PMID 38338919, 2024). "mRNA biomarkers (KRAS, MBD3L2, ACRV1, DPM1) can differentiate pancreatic cancer patients from healthy individuals." (PMID 39958008, 2025). "Studies have identified KRAS, MBD3L2, ACRV1, and DPM1 as biomarkers in salivary mRNA to detect pancreatic cancer with high specificity." (PMID 38202898, 2023). "Biomarker proteins in pancreatic cancer include KRAS (Kirsten Rat Sarcoma Viral Oncogene), MBD3L2 (Methyl-CpG Binding Domain Protein 3 Like 2), DPMI mRNAs (Dolichol phosphate mannose synthase), and ACRV1 (Acrosomal Vesicle Protein 1)." (PMID 39091905, 2024). "In pancreatic cancer, the salivary messenger RNA can be used to detect KRAS, Methyl-CpG Binding Domain Protein 3-Like 2 (MBD3L2), Acrosomal Vesicle Protein 1 (ACRV1) and Dolichyl-Phosphate Mannosyltransferase Subunit 1 (DPM1) with 90% sensitivity and 95% specificity." (PMID 32294884, 2020).
anemia (1 paper, 2024). A reduction in the number of red blood cells, the amount of hemoglobin, and/or the volume of packed red blood cells. "Emerging evidence posits that PAC, by inhibiting ACRV1, is instrumental in mitigating anemia." (PMID 39281381, 2024).
ovarian carcinoma (1 paper, 2025). A malignant neoplasm originating from the surface ovarian epithelium. "To elucidate how the ZNF280A/ACRV1 axis regulates ovarian cancer progression, we performed gene set enrichment analysis (GSEA)." (PMID 41338461, 2025).
prostate carcinoma (1 paper, 2024). A carcinoma that arises from epithelial cells of the prostate gland. "Notably, GDF15 was associated with 16 of 18 diseases studied, whereas ACRV1 (a testis-specific protein involved in spermatogenesis) was only associated with prostate cancer." (PMID 39117878, 2024).
cancer (5 papers, 2015 to 2025). A tumor composed of atypical neoplastic, often pleomorphic cells that invade other tissues. "However, ACRV1, a relatively understudied protein in cancer, emerges as a key player in our study, positively regulating ZNF280A and contributing to OC progression." (PMID 41338461, 2025). "Notably, TCGA database analysis illuminated ACRV1's aberrant upregulation across multiple cancer types, particularly in tumors compared to normal tissues." (PMID 41338461, 2025).
tumor (4 papers, 2016 to 2025). "Biologically, the ZNF280A/ACRV1 axis functions as a metabolic switch that enhances glycolytic capacity, enabling OC cells to adapt to hypoxia and nutrient stress within the tumor microenvironment." (PMID 41338461, 2025). "At present, only a few studies have revealed ACRV1 as a transcription factor involved in tumor migration." (PMID 41338461, 2025).
ACRV1 also shares sentences with these, for which no sentence is quoted: breast carcinoma (1 paper); chronic pancreatitis (1); kidney (1); liver (1); pancreatitis (1); seminoma (1).